SYTL5 (synaptotagmin like 5)
Description:
May act as Rab effector protein and play a role in vesicle trafficking. Binds phospholipids.
Synonyms: SLP5
Tractability: Antibody: UniProt places it where antibodies can reach, with medium confidence; its Gene Ontology location is reachable by antibodies, with medium confidence.
Gene: Protein-coding gene on chromosome X (38,006,515 to 38,128,819, forward strand). Ensembl gene ENSG00000147041.
Subcellular location: Membrane
Subcellular location (Human Protein Atlas): Cytosol; Golgi apparatus
Gene Ontology:
Molecular function: protein binding; neurexin family protein binding; phospholipid binding; small GTPase binding
Biological process: exocytosis; intracellular protein transport
Cellular component: exocytic vesicle; plasma membrane; membrane
Homologues: Orthologues: chimpanzee SYTL5 (99% identical), macaque SYTL5 (97% identical), rabbit SYTL5 (89% identical), pig SYTL5 (86% identical), rat Sytl5 (85% identical), mouse Sytl5 (84% identical), dog SYTL5 (84% identical), guinea pig SYTL5 (83% identical), tropical clawed frog sytl5 (53% identical), zebrafish sytl5 (48% identical). Paralogues in human: SYTL4 (39% identical), SYTL2 (29% identical), SYTL3 (28% identical), SYTL1 (24% identical), RPH3A (21% identical), SYT10 (16% identical), SYT7 (16% identical), SYT6 (15% identical), SYT1 (15% identical), SYT17 (15% identical), SYT9 (15% identical), SYT3 (14% identical), and 19 more.
Diseases named in the same sentence as SYTL5 in open-access papers:
SYTL5 is named in the same sentence as 14 diseases in open-access papers, as found by Europe PMC text mining. Sharing a sentence is not in itself a finding about the gene and the disease. The quoted sentences say what the papers report.
adrenocortical carcinoma (1 paper, 2025). "We observed, using data from GTEx, that the adrenal gland is among the tissues with highest levels of SYTL5 gene expression, and that its expression is reduced in adrenocortical carcinoma samples (TCGA-ACC) when compared to normal adrenal gland tissue." (PMID 41294009, 2025). "Intriguingly, SYTL5 expression is significantly reduced in tumours of the adrenal gland and correlates positively with survival for patients with adrenocortical carcinoma." (PMID 41294009, 2025). "Low SYTL5 expression is related to reduced survival for adrenocortical carcinoma patients." (PMID 41294009, 2025).
cervical cancer (1 paper, 2025). A primary or metastatic malignant neoplasm involving the cervix. "Eventually, we obtained a seven-mRNA–lncRNA gene cluster (four mRNAs: ART3, HRG, MAPT, and SYTL5; three lncRNAs: AC011239.1, AC125616.1, and RUVBL1.AS1) that was mostly relevant to LNM of cervical cancer." (PMID 40444278, 2025). "Among these transcripts, AC125616.1, HRG, MAPT, RUVBL1.AS1, and SYTL5 were found to be upregulated, while AC011239.1 and ART3 were downregulated in cervical cancer patients with LNM compared to those without it." (PMID 40444278, 2025).
COVID-19 (1 paper, 2025). A disease caused by infection with severe acute respiratory syndrome coronavirus 2. "Among the 5 common DEGs, four were significantly downregulated (ERP27, SYTL5, EXTL1, DIO2) and one was upregulated (STXBP6) in the COVID-19 dataset." (PMID 40660393, 2025).
papillary thyroid cancer (1 paper, 2025). "Additionally, SYTL5 was reported to promote the progression of papillary thyroid cancer through the nuclear factor-kappa B (NF-κB) signaling pathway." (PMID 40660393, 2025).
pterygium (1 paper, 2025). A wedge-shaped fibrovascular lesion arising from the bulbar conjunctiva and extending to the cornea. "A similar tendency was observed in pterygium tissues versus normal controls, with a significant decrease in the level of four genes (ERP27, SYTL5, EXTL1, DIO2) and an increment of gene STXBP6." (PMID 40660393, 2025).
synucleinopathies (1 paper, 2016). "Thus, we can speculate that, at least for CC2D1A and SYTL5, the effects observed are not due to cytotoxicity, as membrane integrity is preserved, and these hits can be further tested as candidate therapeutic modulators in synucleinopathies." (PMID 27123591, 2016).
cancer (1 paper, 2025). A tumor composed of atypical neoplastic, often pleomorphic cells that invade other tissues. "The observed switch from OXPHOS to glycolysis in U2OS cells depleted of SYTL5 prompted us to look at cancer patient databases." (PMID 41294009, 2025). "Furthermore, patient survival analysis using data obtained from the TCGA-ACC cohort indicates that low SYTL5 mRNA expression is associated with a significantly reduced survival of ACC patients, suggesting a possible tumour suppressor function for SYTL5 in ACC cancer progression." (PMID 41294009, 2025).
tumour (1 paper, 2025). "A comparison of gene expression levels in normal adrenal gland samples and ACC samples showed that SYTL5 mRNA expression is significantly reduced in tumour samples." (PMID 41294009, 2025).
SYTL5 also shares sentences with these, for which no sentence is quoted: brain disorder (1 paper); infection (1); McLeod syndrome (1); osteosarcoma (1); spermatogenic failure, X-linked, 3 (1); tumours of the adrenal gland (1).